MTOR (mechanistic target of rapamycin kinase)
Diseases named in the same sentence as MTOR in open-access papers (continued):
Sharing a sentence is not in itself a finding about the gene and the disease.
prostate carcinoma (continued). "With studies reporting niclosamide to inhibit NF-kB, mTOR and STAT3 pathway in uveal melanoma, cervical and prostate cancer respectively." (PMID 31383893, 2019). "Recent studies have further established Rab1A as an activator of mTORC1 in CRC, prostate cancer and HCC5,11,27, and also shown a crosstalk between mTOR/S6K1 and Gli128–30." (PMID 31527621, 2019). "It has been reported that the PI3K/Akt/mTOR signaling pathway plays a crucial role in the proteolytic processing of PFK1, from 85 kDa to 49 kDa fragments, in breast and prostate cancer cell lines." (PMID 31141937, 2019). "CNAs at the level of MYC, MYCN, GSK3B, MTOR, and BRCA2 are more frequently detected in germline BRCA2-mutant prostate cancers than in sporadic localized cancers." (PMID 31366128, 2019). "miR-218 reduces VEGF expression in prostate cancer by acting on the mTOR component RICTOR (rapamycin-insensitive companion of mammalian target of rapamycin) and by blocking the RICTOR/mTOR/HIF-1/VEGF signaling pathway." (PMID 31757094, 2019). "Another attractive polyphenol, fisetin inhibits mTOR complexes, PI3K, and Akt activity in prostate cancer cell lines." (PMID 30766532, 2019). "For example, in prostate cancer, inhibition of the PI3K/AKT/mTOR pathway is sufficient to activate autophagy." (PMID 29487530, 2018). "As is the AMPK/mTOR pathway, IKK/NF-κB signaling is constitutively active in prostate cancer due to dysregulation/activation of oncogenic pathways such as Akt or loss of PTEN tumor-suppressor function." (PMID 30041429, 2018). "We showed in prostate cancer cells that RARRES1 is able to induce autophagy, decrease mechanistic target of rapamycin (mTOR) and increase Sirtuin 1 (SIRT1), two important regulators of energy homeostasis." (PMID 30557378, 2018). "For example, we found that the prognostic value of SOX9 and mTOR expression was limited to ERG-positive cancers while the prognostic value of NBS1, SENP145 CD14746 only seen in ERG-negative prostate cancers." (PMID 28515422, 2017). "Resveratrol‐activated autophagy mediated cell death in prostate cancer cells via downregulating of STIM1 and mTOR pathway." (PMID 28675698, 2017). "Therefore, mTOR inhibition might be a potential therapeutic strategy against prostate cancer." (PMID 29228561, 2017). "A dual PI3K/mTOR inhibitor, BEZ235, is also known to enhance the radiosensitivity of prostate cancer cells with reduced EMT/CSC phenotypes." (PMID 28137309, 2017). "TNBC subtypes showed differential sensitivities to cisplatin, bicalutamide (an androgen receptor antagonist used in prostate cancer), and PI3K/mTOR inhibition." (PMID 29108347, 2017). "Ex vivo treatment of a patient-derived xenograft (PDX) of prostate cancer with a combination of AZD7328 and the mTOR inhibitor KU-0063794, significantly reduced tumour frequency upon re-engraftment of tumour cells." (PMID 28915623, 2017). "In prostate cancer, SPS-7 induced an inhibitory effect on mTOR, which downregulated mTOR-dependent phosphorylation of 4EBP1." (PMID 28362357, 2017). "Several promising targeted-therapeutics for prostate cancer (PCa), primarily affecting the androgen receptor (AR) and the PI3K/AKT/mTOR-pathway, are in various phases of development." (PMID 27783994, 2016). "In a pre-clinical prostate cancer in vivo study, PD0325901 was assessed in combination with the mTOR inhibitor rapamycin." (PMID 27046225, 2016). "Importantly, growth arrest specific 6 (GAS6), which influences prostate cancer dormancy, and is secreted by the osteoblastic niche, regulates part of the conversion of DTCs into CSCs through its receptor Mer, by activating the mTOR signaling pathway following cell-to-cell contact." (PMID 27172799, 2016). "Our previous data obtained from prostate cancer cells, ovarian cancer cells and renal carcinoma cells indicated that isoflurane up-regulates the synthesis of HIF-1α via the PI3K/Akt/mTOR pathway and promotes the metastatic potential of cancer." (PMID 27028996, 2016).
prostate carcinoma (continued). "In the original study that produced the ribosome profiling data, PP242 was used as an mTOR inhibitor, which suppressed PC3 cell migration and prostate cancer metastasis." (PMID 27041671, 2016). "Enzalutamide exposure induced autophagic response in prostate cancer cells that operated through activation of AMP-dependent protein kinase (AMPK) and the suppression of mammalian target of rapamycin (mTOR)." (PMID 25705125, 2015). "For example, combining HDAC inhibitors and LY294002 (a PI3K inhibitor) sensitizes a non-small cell lung cancer (NSCLC) xenograft to apoptosis; in prostate cancer, HDAC inhibitor produces greater antitumor activity when combines with PI3K/mTOR inhibitor." (PMID 25669976, 2015). "Accordingly, in two separate mouse models of Pten deletion/elevated mTOR signaling, Pb-Cre;Ptenf/f and K8-CreERT2;Ptenf/f, G6PD levels correlated with prostate cancer progression in vivo." (PMID 24861463, 2014). "Employing the DU-145 prostate cancer cell line, a possible HDAC-triggered histone acetylation connection to the Akt-mTOR axis was investigated." (PMID 24779401, 2014). "To further investigate the relationship between miR-96 and ATG7 or MTOR, we detected miR-96 expression level, ATG7 and MTOR protein levels in 10 prostate cancer tissues." (PMID 25333253, 2014). "Our data suggest that MSeA induces REDD1 and inhibits prostate cancer cell growth in hypoxia despite activation of AKT and dysregulation of mTOR." (PMID 24515947, 2014). "Hence, inactivating mTOR could become an attractive option to treat advanced prostate cancer." (PMID 22782340, 2012). "In prostate cancer cells, survivin expression has been shown to be regulated by IGF-1 stimulated Akt-mTOR signaling, which Is impaired upon simvastatin treatment." (PMID 22974127, 2012). "Concomitant inhibition of mTOR and MNK1 has been reported to efficiently suppress cell proliferation and protein synthesis in prostate cancer cells." (PMID 20539760, 2010). "In the present study, we have shown that resveratrol induced apoptosis in prostate cancer cells through inhibition of PI3K/AKT and mTOR pathway, and activation of FOXO transcription factors." (PMID 21179458, 2010). "An additional xenograft model that we used was the PC-3 human prostate cancer model, since the AKT/mTOR signaling pathway is frequently upregulated in these cancers." (PMID 19401772, 2009). "Interestingly, AR signaling triggers mTOR‐dependent translation of cyclins D1 and D3 but are suppressed in ADT‐responsive prostate cancer cells when deprived of steroids." (PMID 40007440, 2025). "Similarly, in radioresistant prostate cancer cell models, activation of the PI3K/AKT/mTOR pathway promotes EMT and reinforces CSC phenotypes." (PMID 40725100, 2025). "In summary, our results suggest that SESN2 modulates proliferation and EMT in prostate cancer cells, which may be related to the activation of AMPK/mTOR signaling pathway-mediated autophagy." (PMID 40661871, 2025). "To further define this, we evaluated changes in LC3A/B accumulation, LC3B lipidation levels, and mTOR signaling in bafilomycin A1–sensitive (R5) and bafilomycin A1–nonsensitive (R4) prostate cancer organoids over a time-course experiment." (PMID 39919177, 2025). "On the other hand, these defects can prompt prostate cancer cells to activate compensatory signaling pathways, such as the PI3K/AKT/mechanistic target of rapamycin (mTOR) or mitogen-activated protein kinase (MAPK) pathways, to sustain cell survival and progression." (PMID 41079787, 2025). "The down-regulation of AKT1 and mTOR expression and the up-regulation of CASP9 expression implied that the conduction of the Prostate cancer signaling pathway is blocked, then this pathway-mediated proliferation was stalled and apoptosis was significantly increased." (PMID 38326539, 2024). "Inhibiting components of the mTOR pathway, including LAMTOR4, might offer a strategy to inhibit tumor progression and metastasis in prostate cancer." (PMID 39125671, 2024).
prostate carcinoma (continued). "Interestingly, oleocanthal inhibits the upstream signalling of mTOR and MAPK, particularly targeting SMYD2, which plays a crucial role in prostate cancer proliferation and recurrence." (PMID 39203892, 2024). "AKT1, mTOR, and CASP9 were all located at the core of the Prostate cancer signaling pathway." (PMID 38326539, 2024). "Additionally, previous research has revealed that EpCAM forms a complex with p85, the regulatory subunit of PI3K, and promotes tumor progression in prostate cancer and nasopharyngeal carcinoma through the regulation of the PI3K/AKT/mTOR pathway." (PMID 38791091, 2024). "For instance, prostate cancer frequently exhibits disruption of the PI3K/Akt/mTOR pathway, which is independent of androgen receptor (AR) signaling and promotes cell survival and proliferation." (PMID 39199550, 2024). "In addition, activation of the EGFR/MAPK/mTOR/AKT/ERK1/2 signaling pathway in various cancers, such as glioblastoma, endometrial cancer, and prostate cancer can promote cancer cell invasion, metastasis, and drug resistance." (PMID 38762741, 2024). "In prostate cancer, common pathways between HBP and PI3K/AKT/mTOR are observed." (PMID 39337387, 2024). "Despite significant advances in developing pharmacological inhibitors of PI3K/AKT/mTOR kinases, the results from clinical trials in prostate cancer demonstrated severe toxicity and a lack of clinical benefit." (PMID 38611022, 2024). "In prostate cancer, MSI2 can bind to the 3’-UTR region of androgen receptor (AR) mRNA, enhancing its mRNA stability and translation activity, and regulating the PI3K/AKT/mTOR pathway." (PMID 39097735, 2024). "Androgen receptor signaling was reported to promote the PPP through mTOR-mediated upregulation of G6PD in human prostate cancer cell lines, and G6PD expression was closely correlated with prostate cancer progression using two animal models of Pten deletion/elevated mTOR pathway." (PMID 37802999, 2023). "Furthermore, abnormal expression of ALDH1A3 promotes chemotherapy resistance in prostate cancer, via the PI3K/AKT/mTOR axis." (PMID 37551838, 2023). "Earlier research has also shown that CDCA5 might influence cell malignant behavior in prostate cancer, bladder cancer, and hepatocellular carcinoma through modulating PI3K/AKT/mTOR signaling." (PMID 37287817, 2023). "Further, SKI-178 inhibited Akt-mTOR activation and induced JNK activation in prostate cancer cells." (PMID 37604912, 2023). "In addition, the treatment of prostate cancer cells with UA resulted in inhibition of JNK, Akt, mTOR, p70 S6K, 4EBP1, and NF-κB." (PMID 37108576, 2023). "In prostate cancer, metformin was reported to induce the suppression of pro-inflammatory cytokines IL-2, TNF-α, and INF-ɣ, which was correlated with the inhibition of the mTOR Pathway." (PMID 37842429, 2023). "In prostate cancer, CD147 regulates autophagy via the PI3K/Akt/mTOR pathway." (PMID 37720230, 2023). "Having demonstrated a correlation between HER2 and PSMA levels upon PI3K/mTOR inhibition, we questioned whether PSMA expression was dependent on HER2 signaling in PTEN-wt prostate cancer cells." (PMID 35086953, 2022). "GOLM1 promotes HCC, glioma and prostate cancer proliferation and growth through the regulation of the EGFR/PDGFRα/RTK signaling pathway, thus resulting in the activation of PI3K/AKT/mTOR signaling cascade and in the positive feedback loop, already described in the previous section." (PMID 35805075, 2022).
prostate carcinoma (continued). "A combination of chloroquine as an autophagy inhibitor and palladium (II) barbiturate complex results in inhibition of PI3K-AKT signaling, MTOR and MAPK14/p38 upregulation to inhibit protective autophagy and potentiate apoptosis induction in prostate cancer cells." (PMID 35317831, 2022). "In prostate cancer, IMP3 is overexpressed, and it accelerates the cancer’s progression by increasing SMURF1-mediated PTEN ubiquitination, which in turn activates PI3K/AKT/mTOR signaling." (PMID 35366242, 2022). "Recently, plectronthoic acid, a novel compound, demonstrated potent significant anti-tumor activities by inhibiting proliferation, induced G0/G1 phase arrest in prostate cancer (PC3, DU145, and CW22Rv1) cells via upregulation of p21/CIP1 and p27/KIP1, and also suppressed mTOR/S6K signaling pathway." (PMID 36500466, 2022). "Previously, it was shown that PKM2 knockdown in the PKM2-overexpressed prostate cancer cell line DU145 induced autophagic cell death by influencing cellular metabolism and the Akt/mTOR pathway; however, PKM2 knockdown therapy is severely limited in clinical treatment." (PMID 36612260, 2022). "Upon treatment with the dual PI3K/mTOR inhibitor DS-7423, PTEN wild-type prostate cancer CWR22/22RV1 cells upregulate expression of the proteins PSMA, mGluR1, and the tyrosine kinase receptor HER2, while PTEN-mutant LNCaP cells upregulate androgen receptor and HER3." (PMID 35086953, 2022). "It has shown that autophagy was suppressed in lung and prostate carcinoma cell lines when NEDD4 was knocked out and this NEDD4 downregulation significantly increased activated mTOR (p-mTOR) levels, implying that mTOR signaling was involved in NEDD4-mediated autophagy." (PMID 36293239, 2022). "Thus, it seems that prostate cancer progression is controlled by a fine-tuned network between IGF-1-driven integrin-FAK signaling and the Akt-mTOR pathway." (PMID 35053528, 2022). "Akt-mTOR blockage however is not the sole mechanism responsible for prostate cancer cell death by GNE-493." (PMID 35296639, 2022). "In prostate cancer cells, Apl-1 treatment increased PARP cleavage and activated caspase-3 expression, and inhibited the expression of anti-apoptotic proteins p-Akt (ser473), p-mTOR (ser2448), XIAP, and Bcl-2." (PMID 35629355, 2022). "We here discovered that SphK1 protein downregulation and ceramide accumulation, independent of Akt-mTOR inactivation, were also important for prostate cancer cell death by GNE-493." (PMID 35296639, 2022). "The expression of mTOR was upregulated in BLCA and prostate cancer (PRAD) patients (P < 0.05)." (PMID 35082928, 2022). "Several studies have demonstrated that somatic mutations in the PI3K-Akt pathway could coordinate PTEN, mTOR, AR, MAPK, Wnt and TGF-β signaling pathways to play an important role in the tumorigenesis, progression, and treatment in prostate cancer." (PMID 36095024, 2022). "It is possible that its upregulation could promote a disease progression and a metastatic ability of prostate cancer due to deactivation of PTEN protein, a natural inhibitor of PI3K/AKT/mTOR pathway." (PMID 33413466, 2021). "In prostate cancer cells, a possible target for PLT was receptor tyrosine kinase, such as S6 ribosomal protein (rpS6), a key regulator of protein synthesis and a downstream effector of the Akt/mTOR/p70S6K signaling pathway." (PMID 34684834, 2021). "In addition, previous studies have shown that DDIT4 is significantly downregulated in prostate cancer cells and that the induction of DDIT4 expression can regulate MYC, which is a downstream target of the mTOR signaling pathway." (PMID 39697534, 2021). "In addition, resveratrol stimulates ACD in prostate cancer cells via down-regulation of STIM1 and the mTOR pathway." (PMID 33805467, 2021). "Additionally, fixetine can regulate autophagy by acting as an inhibitor of PI3K/Akt/mTOR pathway in human NSCLC cells and prostate cancer." (PMID 34512368, 2021).
prostate carcinoma (continued). "Besides, Reactive Oxygen Species-involved PI3K/AKT/mTOR and ERK/p38 MAPK signaling mediated apoptosis by autophagy inhibition in human prostate cancer cells." (PMID 34486470, 2021). "Here, for the first time in prostate cancer, we investigated the efficacy of a novel multikinase PIM/PI3K/mTOR inhibitor AUM302 and a combination of AZD-1208 and BEZ235, well-researched inhibitors of PIM and PI3K/mTOR, respectively." (PMID 32873828, 2020). "A balance between the activity of the Akt/mTOR and the MAPK/Mnk1 pathway was reported in Prostate cancer cells, where suppression of one pathway was correlated with the activation of another, resulting in a defined translational level of specific mRNAs that supported cancer cell proliferation." (PMID 32603377, 2020). "mTOR inhibitors should reactivate DEPTOR, particularly in prostate cancer with low DEPTOR expression; Second, DEPTOR is subjected to ubiquitylation by SCFβTrCP E3 ubiquitin ligase for proteasome degradation, thus inhibition of SCF E3 by MLN4924 should cause DEPTOR accumulation." (PMID 31685947, 2020). "Akt/mTOR pathway is known to repress BH3-only proteins through the FoxO3A transcription factor phosphorylation and Naftopidil was described to inhibit Akt phosphorylation in gastric and prostate cancer cells." (PMID 32424251, 2020). "In addition, α2M was reported to bind to the GRP78 receptor on the surface of the cell membrane, activating the IGFR and mTOR signaling pathways in prostate cancer, suggesting the involvement of the AKT/mTOR pathway in α2M-mediated cancer development." (PMID 32559179, 2020). "It has been reported that metformin and 5-aminoimidazole-4-carboxamide-1-β-4-ribofuranoside (AICAR), two AMPK agonists, inhibit the proliferation of retinoblastoma and prostate cancer cells via the AMPK/ACC and AMPK/mammalian target of rapamycin (mTOR) signaling pathways." (PMID 33274210, 2020). "Moreover, in prostate cancer, MYC activity was correlated with dysregulation of the PI3K/AKT/mTOR pathway, which induced cellular survival." (PMID 32933107, 2020). "Another significant finding was that docetaxel treatment repressed KLF5 expression through AMPK/mTOR/p70S6K signaling pathway resulting in increased BECN1, induction of cell autophagy, and promotion of cell survival in castration-resistant prostate cancer cells." (PMID 31534497, 2019). "Moreover, activation of the PI3K/Akt/mTOR pathway was also reported to be involved in epithelial mesenchymal transition (EMT) and cancer stem cells (CSCs) in prostate cancer radioresistance." (PMID 30754640, 2019). "In prostate cancer, docetaxel treatment repressed KLF5 expression via AMPK/mTOR/p70S6K signaling pathway, which may lead to increased BECN1 expression, induction of cell autophagy and promotion of cell survival." (PMID 31534497, 2019). "Indeed, it has recently been documented that the Akt-mTOR axis communicates with HDAC-driven acetylation of histones H3 and H4 in prostate cancer cells." (PMID 31010254, 2019). "Furthermore, intracellular ROS play vital roles in PI3K/AKT/mTOR inactivation in human THP-1 monocytes and human prostate cancer cells." (PMID 31223424, 2019). "Our results indicate that in prostate cancer, docetaxel treatment represses KLF5 expression through AMPK/mTOR/p70S6K signaling pathway, which may lead to increase of BECN1, induction of cell autophagy, and promotion of cell survival." (PMID 31534497, 2019). "In prostate cancer, IGF-1 induced survivin expression via activation of the mTOR/p70S6K axis, leading to increased translation of pre-existing survivin mRNA; this process was inhibited by introduction of a p70S6K siRNA and by the mTOR inhibitor rapamycin." (PMID 30729097, 2019). "AAP-H exhibited anticancer activity on DU-145 prostate cancer cells by targeting the PI3K/AKT/mTOR signaling pathway and was not toxic for normal fibroblast cells." (PMID 30208576, 2018).